CD4 (CD4 molecule)
Diseases named in the same sentence as CD4 in open-access papers (continued):
Sharing a sentence is not in itself a finding about the gene and the disease.
Cognitive impairment (continued). "Combined with our results, we speculated that adaptive immunity may be involved in the pathological process of cognitive impairment after cerebral ischemia, especially T cells and CD4+ helper T cells." (PMID 34349636, 2021). "In Chinese ALS patients, blood CD4+ T lymphocyte might help evaluate cognitive impairment along with age and education level." (PMID 33845794, 2021). "However, after the acupuncture treatment, the proportion of T cells and CD4+ helper T cells increased to a certain extent, and the cognitive impairment was improved." (PMID 34349636, 2021). "The abnormal function of CD4 + T cells may lead to serious cognitive impairment, and some clinical evidence has also proven that the proportion of T cells and CD4+ helper T cells decreased in the peripheral blood of patients with VD." (PMID 34349636, 2021). "Risk factors associated with HIV-associated cognitive impairment include longer duration of HIV, older age, low nadir CD4 count, CD4 count less than 350, persistent viremia, substance abuse, lower educational level, and hepatitis C coinfection." (PMID 31214916, 2019). "The development of brain abnormalities and cognitive deficits in HIV+ patients may be related to parameters such as the lowest CD4 lymphocyte cell count in blood (nadir CD4), detectable plasma HIV RNA level, or duration of cART." (PMID 30298203, 2019). "Interestingly, mild cognitive impairment (MCI) and mild forms of AD are associated with a greater number of activated CD4+ and CD8+ T cells in the cerebrospinal fluid (CSF), supporting a role for the migration of activated T cells into the brain during AD27." (PMID 31427644, 2019). "Multivariate logistic regression analysis, using as dependent variable MHE and as independent variables CD4+T cell subsets, showed that the percentages of CD4+CD28− population and of CD69+ cells over the same population were associated with cognitive impairment measured by PHES." (PMID 28751644, 2017). "Despite many years on therapy, HIV-infected patients maintain elevated levels of immune activation and inflammation, which is linked to the increased incidence of cardiovascular diseases, bone disorders, cognitive impairment and other age-related diseases despite low viral loads and high CD4 counts." (PMID 26402620, 2015). "The results did not confirm this, and neither lower nadir nor current CD4 T-cell counts were a risk factor for cognitive impairment." (PMID 21365002, 2011). "Recent research has suggested that cognitive impairment may become more likely the lower the value of the nadir CD4 cell count." (PMID 20406460, 2010). "The clinical implications of the paucity of CD4/TH17 cells in cognitive impairment are unknown." (PMID 37901041, 2023). "Patients with creatinine <60.75 (μmol/L), chloride <106.25 (mmol/L), CD4+ICOS+ ≥11.2%, CD19+PD-L1+ ≥12.35%, plasma sICOSL≥286.37 ng/mL, CSF sugar content ≥3.775 (mmol/L), and those with cognitive impairment are more likely to be diagnosed with AE." (PMID 40352922, 2025). "In contrast, abnormal psychological behaviors, cognitive impairments, serum LDH, serum calcium, CSF glucose, serum oligoclonal bands (OCBs), CD4+ICOS+, CD4+CXCR5+ICOS+, CD19+PD-L1+, and plasma sICOSL were more prominent in the early AE group." (PMID 40352922, 2025). "Patients with elevated levels of CSF glucose and plasma sICOSL, increased percentages of peripheral blood CD4+ICOS+ and CD19+PD-L1+, and symptoms of cognitive impairment were more likely to be diagnosed with AE." (PMID 40352922, 2025). "Immune cell infiltration analysis indicated potential involvement of M1 macrophages, NK cells resting, T cells CD4 memory, and T cells CD8 naive in the process of cognitive impairment." (PMID 39286150, 2024).
Cognitive impairment (continued). "The study examined the interaction between five hub genes (Cxcl10, Gbp2, Cxcl12, Cxcr3, Ifih1) and four distinct immune cell types (M1 macrophages, NK resting cells, memory CD4 T cells, naive CD8 T cells) in mice brain tissues affected by cognitive impairment." (PMID 39286150, 2024). "Surprisingly, we observed an increase in functional CD4+ and CD8+ T cells in amyloid positive cognitively normal participants, while those from amyloid positive mild cognitive impairment subjects had a dramatic increase in exhausted T cells." (PMID 37737298, 2023). "We observed an increase in differentiated CD4+ and CD8+ T cell phenotypes in amyloid positive participants with mild cognitive impairment." (PMID 37737298, 2023). "Women with cognitive impairment had similar frequencies of total (CD3+) or CD8+ T cells, but fewer CD4+ T cells, which explain the lower ratio of CD4+/CD8+ T cells compared with unimpaired women." (PMID 37901041, 2023). "We later combined data from these analyses to investigate MRI glymphatic correlates of cognitive impairment and other clinical tests of HIV (CD4+ T-cell counts and CD4+/CD8+ ratio)." (PMID 35359662, 2022). "Previous studies have shown that the elevated levels of activated CD4+ T cells and CD8+ T cells in peripheral blood is closely related to cognitive defects and MRI changes of specific brain regions in AD patients." (PMID 34447367, 2021). "For example, CD4+ and CD8+ (including CD8+ naive T cells, CD8+ T cells, and CD8+ TCM) cells were significantly lower in AD and patients with mild cognitive impairment." (PMID 34924996, 2021). "Furthermore, we developed an early differential diagnosis model based on serum creatinine, chloride, peripheral blood CD4+ICOS+, CD19+PD-L1+, plasma sICOSL, CSF glucose, fever, nausea and vomiting, headache, and cognitive impairment." (PMID 40352922, 2025). "Indeed, a reduced production and increased depletion of naive and central memory CD4+ T cells seems to characterize advanced presentation of HIV infection and cognitive impairment." (PMID 38704619, 2024). "Comparisons of autophagy-related gene 5 (ATG5) level and CD4+ T-cell subset between patients with and without cognition impairment." (PMID 38511768, 2024). "Taken together, findings indicate that CD4 nadir-related cognitive deficits do not worsen significantly over time." (PMID 38856821, 2024). "We found that amyloid positive mild cognitive impairment (APMCI) participants contained more differentiated phenotype CD4+ and CD8+ T cells than amyloid negative cognitively normal participants (ANCN)." (PMID 37737298, 2023). "While the paucity of CD4/TH17-related markers were notable at earlier stages of disease in women, TH17 cytokine production was also impaired in men with increasing severity of cognitive impairment." (PMID 37901041, 2023). "Similarly, previous studies report that learning, memory, and motor functioning are among the domains in which cognitive impairment is more common among WWH vs. MWH and these differences persisted after adjusting for HIV RNA and CD4 counts." (PMID 33329301, 2020). "Nadir CD4 cell count is the lowest point to which CD4 count has dropped due to HIV infection, i.e., the greatest immunosuppression, and is a particularly significant predictor of neurological complications and cognitive impairment." (PMID 30298203, 2019). "CD4+CD25+Foxp3+ T cells were also elevated in AD patients, which may be related to AD progression, as patients with a mild cognitive impairment (MCI) show lower CD4+CD25+Foxp3+ T-cell activity than AD patients." (PMID 27964740, 2016). "However, despite low replication and normal CD4 counts, 50–70 % of the HIV-infected population shows some signs of cognitive impairment." (PMID 26934876, 2016). "In addition, the IL-13 release in vitro was significantly increased from CD4+ T cells isolated from the MCI patients compared to those from patients without cognitive impairment." (PMID 37373554, 2023).
Cognitive impairment (continued). "However, our data was significant for a negative correlation between CSF NFL and plasma CD4+ T-lymphocyte count across all strata of cognitive impairment, as well as a positive correlation between CSF NFL and plasma HIV-1 RNA viral load." (PMID 25776526, 2015). "Our study describes the novel relationship between dual expressing PD-1/TIM-3 CD4 and CD8 T cells with neurocognitive impairment and brain atrophy, respectively, and highlights NCR-expressing T cells as a potential novel target that may reverse cognitive impairment in HIV among PLWH on ART." (PMID 38949728, 2024). "Additionally, HIV infection could induce neuroinflammation through immune activation to cause similar symptoms, but the patient's CD4 count was 262.55 cells/μL (not severely suppressed), ART had not been initiated, and there was no cognitive impairment, which did not support HIV-related neuropathy." (PMID 40860903, 2025). "In our patients, we found significant reduction of total T lymphocyte, CD4+ T and CD8+ T lymphocyte, and total B lymphocyte in the ALS patients with cognitive impairment compared to those without." (PMID 33845794, 2021). "Among 81 ALS patients, we compared the demographic, clinical, and peripheral levels of total T lymphocyte, CD4+ T lymphocyte, CD8+ T lymphocyte, B lymphocyte, and NK cell between those with cognitive impairment (ALS-ci) and those without (ALS-nci)." (PMID 33845794, 2021). "Although the number of CD4+ T lymphocyte was not correlated with the ECAS total score, it was a significant predictor of cognitive impairment in ALS patients along with older age at testing and lower education level." (PMID 33845794, 2021).
lupus nephritis (82 papers, 2010 to 2025). Glomerulonephritis in the context of systemic lupus erythematosus. "The aim of this study was to investigate the effect of IL-15 on functional properties and associated renal damage of cytotoxic CD4 + CD28− T cell in lupus nephritis (LN)." (PMID 36320075, 2022). "Dose reduction or even withdrawal of MMF should be considered if lymphocytes continue to decline, or CD4 + T cells are less than 200/ μL (Chinese Guidelines for Diagnostic and Treatment of Lupus Nephritis Writing Group, 2019)." (PMID 34552479, 2021). "During disease progression of lupus nephritis, a higher expression of inhibitory receptor PD-1 was associated with a lower degree of CD4+ Tmem-cell functionality regarding IL-2, TNF-α and IFN-γ expression." (PMID 32441253, 2020). "Previously, we reported an association of increased levels of costimulatory markers on CD4+ cells with lupus nephritis." (PMID 20653937, 2010). "Thus, for example, the effect of methylprednisolone on improving lupus nephritis was also associated with the rebalancing of Splenic CD4+ cells with a significant reduction in Th17 populations compared to controls in an experimental study." (PMID 34540858, 2021). "Treg CD4+Foxp3 secretes an abundant amount of cytokines that proliferate CD4 T-cells specific towards nuclear antigen, such as nucleosome, which is known as pathogenic antibody in lupus nephritis." (PMID 30858943, 2019). "G-CSF treatment ameliorated lupus nephritis, and preferential expansion of CD4+CD25+Foxp3+ Tregs instead of MDSC may be the underlying mechanism." (PMID 27846813, 2016). "In lupus nephritis (LN), mangiferin increases the proportion of CD4+Foxp3+ Tregs and inhibits the mTOR/p70S6K pathway in FasL-deficient B6/gld mice, serving as a therapeutic agent for LN." (PMID 41458964, 2025). "Anti-nucleosome antibodies and nucleosome-specific CD4 positive T cells appear earliest preceding anti-dsDNA in lupus nephritis." (PMID 38460182, 2025). "CLT has also been reported to alleviate murine lupus nephritis via inducting CD4+Foxp3+ regulatory T cells." (PMID 39494325, 2024). "Mechanistic and observational studies suggest that modulation through B cells and CD4 T cells can effectively suppress the development of IgA nephropathy and lupus nephritis, findings consistent with our study results." (PMID 38765814, 2024). "In vitro-differentiated CD103+Foxp3+CD8+ Tregs suppressed CD4 T-cell responses and ameliorated CD4 T-cell-mediated lupus nephritis by directly suppressing B-cell responses." (PMID 37907738, 2023). "Rapamycin treatment alleviated SLE-like experimental lupus nephritis by the recovery of IL-2 production, which modulated the maintenance and expansion of CD4+FOXP3+ Tregs, in turn inhibiting activated effector T cells." (PMID 36979928, 2023). "treated mice with lupus nephritis using DPSCs; the mice showed a reduction in IgG and IgM deposition in the glomeruli, a significant decrease in the number of CD4+ T cells that produce IFN-γ, and a reduction in perivascular inflammatory infiltrates." (PMID 38077342, 2023). "Interleukin-10 receptor expression and signaling are downregulated in CD4+ T cells from lupus nephritis patients with higher clinical scores." (PMID 36077487, 2022). "In terms of the pathogenicity and fate of infiltrated monocytes, murine kidney CD11c+ myeloid cells, which were differentiated from Ly6Clo monocytes, were reported to promote lupus nephritis by interacting with CD4+ T cells." (PMID 35371102, 2022). "On the one hand, renal infiltration of CD4+ T cells promoted the development of Lupus nephritis in MRL/lpr mice." (PMID 35908050, 2022). "We focused on ABC-like memory B-cells, TFH, TPH and PD-1high CD4+ T cells in 10 lupus nephritis and 5 non-lupus nephritis SLE patients." (PMID 35464461, 2022).
lupus nephritis (continued). "Quercetin is a natural flavonoid with anti-inflammatory, antioxidant, immunomodulatory, and neuroprotective properties, which can inhibit CD4 T cell activation and anti-inflammatory effects of macrophages to improve the symptoms in lupus nephritis (LN) mice." (PMID 35097123, 2022). "According to reports, CD4+ T cells mediated the induction of autoantibodies to aggravate lupus nephritis." (PMID 36467552, 2022). "Some kidney diseases, such as lupus nephritis, were reported to have a reduction of peripheral blood CD4+T cells and CD4+/CD8+ T cell ratio compared with that of healthy individuals." (PMID 34568395, 2021). "The frequencies of TNF-α+ Tmem cells within the IFN-γ+ PD-1+ CD4+ subpopulations were reduced with lupus nephritis, similar to CD8+ Tmem cells in chronic infections." (PMID 32441253, 2020). "Immunohistochemistry of renal biopsy specimens obtained from 6 patients with lupus nephritis and 5 with IgA nephropathy was conducted to detect IL-17A-expressing CD4+Foxp3+ cells." (PMID 32317002, 2020). "Overall, our experiments show that antigen-specific CD4+ T cells targeting renally expressed antigens arise in human lupus nephritis and correlate with disease activity and are mainly of the Th1 subset." (PMID 33277543, 2020). "For example, an increased expression level of OX40 on CD4+ T cells is closely correlated with disease activity and lupus nephritis, and serum levels of OX40L are positively correlated with anti­dsDNA levels in SLE patients." (PMID 30944836, 2019). "Peripheral unstimulated CD134+ and PD-1+ CD4+ T-cells were significantly increased in patients with lupus nephritis." (PMID 31331400, 2019). "G-CSF treatment ameliorated lupus nephritis through the preferential expansion of CD4+CD25+Foxp3+ Tregs." (PMID 27846813, 2016). "The balance among the Th1, Th2, and Th17 peripheral blood CD4 cells in patients with lupus nephritis is the critical determinants for histopathology picture of LN." (PMID 27738386, 2016). "CD4+CD25-Foxp3+ T cells were also detectable in the urine sediment of a patient with lupus nephritis." (PMID 24774748, 2014). "Our data reveal that CD4+CD25-Foxp3+ that share phenotypic characteristics with regulatory T cells are increased in patients with lupus nephritis." (PMID 24774748, 2014). "In particular, CD8+ cytotoxic T cells (CD8+ Tc1 cells) and CD4+ Th1 cells are thought to contribute to the progression of lupus glomerulonephritis and vasculitis through release of inflammatory cytokines such as TNFα and INFγ." (PMID 25400916, 2013). "OX40 expression on CD4+ T-cells had a higher sensitivity and specificity in diagnosing lupus nephritis than both OX40L and anti–double-stranded DNA levels." (PMID 21245596, 2011). "Infiltrates of IL-17 producing T cells, including CD4+ and DN T cells, have been found in lupus nephritis." (PMID 20334681, 2010). "Patients with lupus nephritis expressed higher levels of CD134 on peripheral blood CD4+ T-cells as compared to HC (68.08 ± 7.52% vs. 59.27 ± 8.18%, P = 0.027)." (PMID 20653937, 2010). "Patients with lupus nephritis showed significantly higher levels of CD80 expression on CD4+CCR6+ cells in comparison to healthy controls (22.13 ± 10.58% vs. 18.86 ± 3.82%, P = 0.02)." (PMID 20653937, 2010). "Additionally, IgA nephropathy and lupus nephritis exhibit aberrant B-cell and CD4 T-cell infiltration." (PMID 38765814, 2024). "A recent study on lupus nephritis provided data supporting a theory that IL-15 could be a major factor for enhancement of cytotoxic activity of CD4-positive CD28-negative T cells." (PMID 37108157, 2023). "Renal CD4+ memory Th cells are skewed towards a Th1/17 phenotype, which may be relevant to Th17-related kidney diseases including glomerulonephritis, lupus nephritis, and rejection." (PMID 36496458, 2022). "CD4+Foxp3+IL-17A+ cell infiltration was found in renal biopsy specimens of active lupus nephritis." (PMID 35197962, 2021).